TRPS1 (transcriptional repressor GATA binding 1)
Diseases named in the same sentence as TRPS1 in open-access papers (continued):
Sharing a sentence is not in itself a finding about the gene and the disease.
breast carcinoma (continued). "We introduced an inducible degron tag into the native TRPS1 locus within a luminal breast cancer cell line to identify the direct targets of TRPS1 and determine how TRPS1 mechanistically regulates gene expression." (PMID 37461612, 2023). "The FRA-1 effect on TRPS1 is mediated by the miR-221/222 oncomiRs, which are overexpressed in basal-like breast cancers." (PMID 37176013, 2023). "The trichorhinophalangeal syndrome type 1 (TRPS1) immunohistochemical (IHC) stain has increased in use in recent years as a marker for breast carcinomas." (PMID 37366800, 2023). "For instance, TRPS1, a highly sensitive and specific marker for breast carcinoma, especially for triple-negative breast carcinoma, was found to be a reliable marker for predicted breast carcinomas in our cohort (75.0%)." (PMID 38041048, 2023). "For instance, REST is a crucial regulator for acquiring EMT-like and stemness, and TRPS1 positively correlates with E-cadherin and β-catenin expression in ERα-positive breast cancer cells." (PMID 37190063, 2023). "On the contrary, depletion of TRPS1 inhibited cell proliferation induced by MPA treatment in T47D cells and transfecting with the TRPS1 plasmid accelerated progesterone-driven breast cancer cell growth." (PMID 37344459, 2023). "Currently, the transcription factor SRY box 10 (SOX-10) and the type 1 trichorhinophalangeal syndrome (TRPS-1), as markers of breast cancer diagnosis by IHC, have been included in TNBC diagnostic assays." (PMID 37686305, 2023). "TRPS1, which anticorrelates with FOSL1 in aggressive breast carcinoma (TCGA expression Atlas), encodes for a GATA-type zinc-finger transcription repressor playing cell context-dependent roles." (PMID 37176013, 2023). "A recent study showed that TRPS1 staining is a highly sensitive and specific marker for breast carcinoma." (PMID 36810569, 2023). "Subsequently, human endometrial cancer/breast cancer xenograft models were established to investigate the regulation effect of cofactor TRPS1 in vivo." (PMID 37344459, 2023). "The numbers are obviously low, but all were positive for TRPS1, in keeping with this marker being a useful pan-breast cancer marker, including TNBCs and basal-like cancers." (PMID 37012444, 2023). "They concluded as TRPS1 is a highly sensitive and specific marker for breast carcinomas, including TNBC." (PMID 37012444, 2023). "The transcription factor TRPS1 with classic GATA-type zinc fingers, was known to repress transcription, prior studies had also hinted at roles for overexpressed TRPS1 in tumorigenesis, including breast cancer." (PMID 37344459, 2023). "A recent study demonstrated the immunohistochemistry (IHC) of TRPS1 in various breast tumors and proposed this IHC stain as a highly sensitive and specific marker for mammary tumors." (PMID 36810569, 2023). "All these data suggest that both MGP and TRPS1 maintain excellent sensitivity in different subtypes of metaplastic breast carcinomas." (PMID 36284362, 2022). "Recent investigations have proved that TRPS1 is commonly overexpressed in several kinds of malignant illnesses, such as breast carcinoma, hepatocellular cancer, prostatic carcinoma, and colon cancer." (PMID 36238488, 2022). "When using MGP, GATA3, and TRPS1 as a novel IHC panel, 93.0% of breast carcinomas were positive for at least two markers, and only 9 cases were negative for all three markers." (PMID 36284362, 2022). "MGP was verified as a reliable marker with extremely high sensitivity in all subtypes of breast carcinoma (87.3–91.2%), which is comparable to TRPS1 and much higher than GATA3 in HER2+ and TNBC subtypes." (PMID 36284362, 2022). "In breast cancer cells, where TRPS1 is frequently overexpressed and amplified, TRPS1 physically interacts with TEAD and colocalizes with TEAD-bound loci." (PMID 34439395, 2021).
breast carcinoma (continued). "Focusing on hormone-sensitive breast cancer, TRPS1 was proposed to specifically recruit NuRD in order to suppress cell migration and invasion genes, thereby reducing the metastatic potential of breast cancer cells." (PMID 33284960, 2021). "TRPS1 is a transcription repressor of GATA-regulated genes, which promotes EMT in breast cancer and its expression is associated with clinical outcome in this cancer." (PMID 33558504, 2021). "TRPS1 is a common oncogene that plays an important role in controlling cell cycle during breast cancer." (PMID 32318558, 2020). "Amplification of TRPS1 was associated with a substantially decreased survival probability of the affected patients, suggesting that TRPS1 behaves as an oncogene in human breast cancer patients." (PMID 30082728, 2018). "Here, the authors perform an unbiased genome wide CRISPR screen and identify Trichorhinophalangeal syndrome 1 (TRPS1) that represses YAP/TEAD activity independently of Hippo pathway in breast cancer." (PMID 30082728, 2018). "The analysis showed that cell adhesion and regulation of cell migration functions were enriched, suggesting an important role of TRPS1 in regulating metastatic abilities of breast cancer cells." (PMID 30563971, 2018). "Consistent with an oncogenic role of TRPS1, its amplification is predictive for the survival of breast cancer patients, anti-correlated with YAP activity and with the frequency of tumour-infiltrating immune cells." (PMID 30082728, 2018). "It will not only be important to uncover the role of TRPS1 during breast cancer, but also to understand its role during normal breast development and tissue maintenance using suitable mouse models." (PMID 30082728, 2018). "In this study, we addressed how TRPS1 functions as a transcriptional repressor and contributes to breast cancer pathogenesis." (PMID 30563971, 2018). "We have shown that TRPS1 reduced the metastatic ability of breast cancer cells by involving decommission of TP63 enhancer and repressing ΔNp63 expression." (PMID 30563971, 2018). "TRPS1 is commonly amplified in breast cancer, which suggests that restrained YAP activity favours tumour growth." (PMID 30082728, 2018). "Our results help in understanding the complexity of the functions of GATA family members and support the pursuit of TRPS1, NuRD, and ΔNp63 as the potential prognostic indicators and/or therapeutic targets of breast cancer." (PMID 30563971, 2018). "Recently, TRPS1 was identified by in vivo transposon-based forward genetic screening as a potential breast cancer driver gene by our group and others." (PMID 30071870, 2018). "Elevated TRPS1 expression has been observed in human cancers, including osteosarcoma, colon cancer, and breast cancer." (PMID 30071870, 2018). "To explore the function of TRPS1, we used luminal breast cancer cells MCF7, T47D, and BT474 with elevated TRPS1 as model cell lines." (PMID 30071870, 2018). "TRPS1 is co-amplified with MYC in breast carcinomas with an increased proliferation rate, and silencing TRPS1 reduces proliferation of BT474 cells." (PMID 30071870, 2018). "In conclusion, GATA3 and TRPS1 are distinctly high-expressed in breast cancer versus normal controls and predict better survival in patients with BC." (PMID 28423734, 2017). "TRPS1 over-expressed in the breast cancer cell lines with high level of ERBB2 expression, while under-expressed in those with low level or negative ERBB2 expression (p=0.003)." (PMID 28423734, 2017). "TRPS1 affects cell proliferation, differentiation and apoptosis essentially in bone and cartilage and it overexpressed in breast cancer." (PMID 26183398, 2015). "TRPS1 was proposed to have a prognostic value in early stage breast cancer and to promote tumor progression." (PMID 26183398, 2015). "Our studies provide a template for the preclinical evaluation of critical Cath-D/TRPS1 target genes involved in the progression of specific breast cancer subtypes." (PMID 26183398, 2015).
breast carcinoma (continued). "TRPS1 expression was decreased between Grade 1 and Grade 3 breast cancers and in luminal-B breast cancers." (PMID 25277197, 2014). "Here we provide evidence that TRPS1 promotes the proliferation of BT474 breast cancer cells by affecting cell cycle progression." (PMID 25277197, 2014). "TRPS1 expression also systematically decreased from Grade 1 to Grade 3 breast cancer across the entire cohort, as well as in luminal-B breast cancers when examined separately." (PMID 25277197, 2014). "In primary breast tumor samples, elevated expression of Trps1 was observed in luminal-A and -B breast cancers." (PMID 25277197, 2014). "Among the investigated breast cancer cell lines, TRPS1 expression was highest in BT474 cells and lesser in MCF7 cells, whereas it was almost undetectable in MDA-MB-231 cells." (PMID 25277197, 2014). "Overall, our findings are in line with previous results, showing that TRPS1 has both an oncogenic and a tumor suppressor role in breast cancer development." (PMID 25277197, 2014). "Our objective was to elucidate the different roles and clinical relevance of TRPS1 in different estrogen receptor (ER) expression subtypes of breast cancer." (PMID 24934762, 2014). "A quantitative immunohistochemistry (qIHC) approach found that TRPS1 protein expression in breast cancers above a certain threshold was correlated with markedly improved overall survival." (PMID 24709795, 2013). "Two studies have shown that two different GATA factors, GATA-3 and tricho-rhino-phalangeal syndrome type 1 (TRPS1), activate E-cadherin gene expression in breast cancer cells." (PMID 24040319, 2013). "Based on a comprehensive differential gene expression screen, Trps1 has been revealed as one of the most prevalent genes that is specifically overexpressed in breast cancer." (PMID 24709795, 2013). "Trps1 is a target gene of miR-221/222 in luminally originated breast cancer cells counteracting EMT that restrains tumor cells from metastasis." (PMID 24709795, 2013). "This region delimited from centromere to telomere by TRPS1 and PVT1 contains MYC, two colorectal cancer risk loci, rs16892766 (8q23.3) and rs6983267 (8q24.21), and one breast cancer risk locus rs13281615 (8q24.21)." (PMID 20932292, 2010). "Recently, TRPS-1 protein has been found to be dramatically overexpressed in >90% of early and late-stage breast cancers." (PMID 20969773, 2010). "Furthermore, under various experimental conditions, the specificity of TRPS1 for breast cancer or TNBC specifically was consistently less than 70%." (PMID 40822238, 2025). "In hormone receptor-positive tumors, GATA3 modulates cell proliferation through estrogen-responsive genes (e.g., ESR1 and GREB1), while TRPS1 may similarly influence hormonal signaling in breast cancer." (PMID 40969274, 2025). "In addition, we did not study TRPS1 expression at molecular/mRNA level or evaluated the prognostic significance of TRPS1 in breast cancers." (PMID 40025593, 2025). "Over the past decade, TRPS1 has been studied as a new breast cancer marker." (PMID 40822238, 2025). "Of these, TRPS1 was employed in the evaluation of 17 breast specimens to distinguish whether the tumor was a primary breast carcinoma (n = 14) or an extra-mammary metastasis to the breast (n = 3)." (PMID 40025593, 2025). "This is consistent with the fact that 9.6% of primary breast carcinomas are TRPS1-negative, and indicates that, even though strong TRPS1 positivity favors the mammary origin of a metastatic tumor, negativity of TRPS1 cannot completely rule out this origin of a cutaneous metastasis." (PMID 39449380, 2024). "Similarly, in bone metastases, TRPS1 can help to differentiate metastatic breast cancer from primary bone malignancies, such as osteosarcomas." (PMID 39518009, 2024). "In addition, gene sets associated with low grade breast cancer were upregulated in shTRPS1 luminal cells (LCs) which points to the fact that TRPS1 can be an oncogene in breast cancer." (PMID 38702730, 2024).
breast carcinoma (continued). "TRPS1 has recently emerged as an oncogene in specific breast cancer types." (PMID 38702730, 2024). "TRPS1 may also be useful in distinguishing luminal-type breast cancers from some gynecological malignancies, where ER/PR expression may pose diagnostic pitfalls." (PMID 39518009, 2024). "Until recently, TRPS1 has been found to be more specific for breast cancer, reducing the likelihood of misdiagnosis in cases where GATA3 expression might overlap with non-breast malignancies." (PMID 39518009, 2024). "The broader applicability of TRPS1 across breast cancer subtypes makes it a more robust marker in both routine and challenging cases, particularly in poorly differentiated tumors or TNBC, where SOX10 alone may not provide sufficient diagnostic clarity." (PMID 39518009, 2024). "In cases of TRPS1-negative breast carcinomas, over-reliance on TRPS1 alone could lead to a missed diagnosis or misclassification." (PMID 39518009, 2024). "The transcription factor TRPS1 is a context-dependent oncogene in breast cancer." (PMID 38702730, 2024). "TRPS1 may also be considered as a target to improve chemo-sensitization strategies and, consequently, clinical outcomes for breast cancer patients." (PMID 39276941, 2024). "Based on this result, we hypothesized that perturbation of TRPS1 in luminal breast cancer cell lines would affect cell fitness." (PMID 38377146, 2024). "This broad expression profile has positioned TRPS1 as a valuable marker for distinguishing breast cancer from other carcinomas that may metastasize to the breast." (PMID 39518009, 2024). "However, TRPS1 has been found to be expressed in prostate cancer as well, albeit to a lesser extent than in breast cancer." (PMID 39518009, 2024). "Both of these unbiased screens indicate that TRPS1 contributes to luminal breast cancer cell fitness and led us to the hypothesis that TRPS1 influences ER activity or genomic binding." (PMID 38377146, 2024). "The transcriptional program that TRPS1 regulates in breast cancer is not fully understood." (PMID 38377146, 2024). "Several studies have identified subsets of breast carcinomas that lack TRPS1 expression." (PMID 39518009, 2024). "Furthermore, while TRPS1 knockout led to an increase in cell number for most cancer cell lines, luminal breast cancer cell lines were significantly enriched for TRPS1 dependency." (PMID 38377146, 2024). "We classified breast cancer patients from the METABRIC cohort as having high TRPS1 activity if both a) TRPS1-repressed genes are negatively enriched and b) TRPS1-activated genes are positively enriched, relative to all other patients in the cohort (example patient in)." (PMID 38377146, 2024). "The absence of TRPS1 expression in breast carcinomas introduces several potential diagnostic pitfalls." (PMID 39518009, 2024). "The use of the trichorhinophalangeal syndrome type 1 (TRPS1) immunohistochemical stain has increased in routine clinical practice in recent years for its utility as a highly sensitive and specific marker for breast carcinomas, including triple-negative breast carcinomas." (PMID 37366800, 2023). "TRPS1 IHC was reported to show reactivity with breast carcinoma." (PMID 36810569, 2023). "Some studies have suggested that TRPS1 may also act as a critical modulator in mammary epithelial cell growth, differentiation, and breast cancer development via epithelial–mesenchymal transformation, DNA replication, and mitosis." (PMID 36284362, 2022). "The overexpression of TRPS1 promotes aggressiveness in breast cancer models, possibly suggesting that pruning YAP-dependent transcription may provide growth and survival advantages to cancer cells." (PMID 34439395, 2021). "Similarly, a transcriptional repressor TRPS1 and MYC are commonly co-amplified in breast cancers and TRPS1 inhibits YAP-dependent TEAD activity by direct binding." (PMID 31212916, 2019).
breast carcinoma (continued). "To probe the oncogenic potential of TRPS1 in vivo, we made use of an orthotopic tumour model for basal breast cancer in which 4T1 cells, a BALB/C-derived tumour cell line, are transplanted into the mammary fat pad of syngeneic immunocompetent BALB/C mice and tumour growth is monitored over time." (PMID 30082728, 2018). "Our study uncovers TRPS1 as an epigenetic regulator of YAP activity in breast cancer." (PMID 30082728, 2018). "Thus, TRPS1 represses the expression of a large set of YAP target genes in breast cancer cells, but some target genes are affected to a lesser extent or are even spared from this repressive effect." (PMID 30082728, 2018). "To gain more mechanistic insights into TRPS1’s repressive effect on YAP/TEAD target gene expression in breast cancer cells, we performed ChIP-Sequencing for TRPS1 in MCF7 and T47D cells, since genome-wide binding profiles for this factor had not been reported previously." (PMID 30082728, 2018). "Importantly, TRPS1 is commonly amplified in breast cancer, required for efficient tumour growth in vivo and TRPS1 activity is strongly anti-correlated with YAP activity in human breast cancer patients." (PMID 30082728, 2018). "Thus, we analyzed the expression pattern of TRPS1 in sections of breast cancer samples and adjacent normal tissue." (PMID 30082728, 2018). "Since ΔNp63 was repressed by TRPS1, we hypothesized that elevated expression of TRPS1 inhibited migration and invasion of breast cancer cells by repressing the expression of ΔNp63." (PMID 30563971, 2018). "Our data provide mechanistic insights into how TRPS1 functions as a transcription repressor elucidating a new molecular mechanism underlying the transcription regulation of TP63 and providing a link between TRPS1 and migration and invasion of breast cancer cells." (PMID 30563971, 2018). "In addition, CCLE analysis was consistent with that of ONCOMINE demonstrating that GATA3 and TRPS1 were distinctively up-regulated in breast cancer cell lines, while other GATA members were present at a low transcription level or absent in breast cancer cells." (PMID 28423734, 2017). "Of noteworthy, the results demonstrated that TRPS1 high mRNA expression was significantly correlated to longer RFS in patients who have received chemotherapy (HR=0.6, p=0.032), indicating a potential role of TRPS1 in contribution to chemosensitivity in breast cancer." (PMID 28423734, 2017). "Moreover, the analysis also demonstrated that the transcription level of TRPS1 was significantly elevated in breast cancer versus." (PMID 28423734, 2017). "Therefore, it is extrapolated that TRPS1 might be a favorable predictor of chemosensitivity in BC, with underlying mechanism possibly relates to suppression of EMT in breast cancer." (PMID 28423734, 2017). "Moreover, TRPS1 is overexpressed in breast cancer and its expression is linked to the ER+, GATA3 and HER2 status and to the EMT-negative phenotype, as shown here for TRPS1 and Cath-D." (PMID 26183398, 2015). "The MYC oncogene is co-amplified with TRPS1 in breast carcinomas with increased proliferation rate." (PMID 26183398, 2015). "Of note, in the polyoma middle-T antigen transgenic model of luminal ER+ breast cancer, TRPS1 mRNA expression was significantly up-regulated (8-fold) in the earliest hyperplastic lesions in 5-week/old transgenic mice compared to mammary glands from wild type mice." (PMID 26183398, 2015). "TRPS1 can be a prognostic marker depending on the type of breast cancer." (PMID 24934762, 2014). "However, further studies with large number of tumours and breast cancer cell lines are required to validate the precise function of TRPS1 gene in breast cancer." (PMID 24934762, 2014). "Finally, we show a higher expression of TRPS1 in luminal breast cancer cells and luminal breast cancer patient samples as compared with basal breast cancer cells and basal breast cancers patient samples, respectively." (PMID 25277197, 2014).